INS (insulin)
Diseases named in the same sentence as INS in open-access papers (continued):
Sharing a sentence is not in itself a finding about the gene and the disease.
type 2 diabetes (continued). "As muscle takes up the majority of meal‐related carbohydrate intake, muscle insulin resistance is a critical determinant of glycemia and contributes to the development of type 2 diabetes once insulin demand exceeds pancreatic supply." (PMID 24843075, 2014). "Of the 493 participants, 441 (89%) had been diagnosed with type 2 diabetes >5 years ago, and 164 participants (33%) were treated with insulin." (PMID 24367063, 2014). "The classification and pathogenesis of type II diabetes involves abnormalities in glucose and lipid metabolism, inadequate insulin secretion from pancreatic beta-cells, and resistance to insulin activity." (PMID 25401101, 2014). "Thiazolidinediones (TZDs), peroxisome proliferator-activated receptor (PPAR)-γ agonists, are the first drugs that improve insulin sensitivity in skeletal muscle and reduce hepatic glucose production in patients with type 2 diabetes mellitus (T2DM)." (PMID 24736628, 2014). "It potentiates insulin secretion, blocks glucagon release and increases satiety, but cannot be used directly as a therapy for Type 2 diabetes due to its short (2 minute) half life." (PMID 24835252, 2014). "This randomized, open-label study compared insulin lispro, sulfonylurea, and NPH insulin in patients with type 2 diabetes who required treatment with insulin after failure of an oral agent therapy." (PMID 23959960, 2014). "GLP-1 contributes to myriad of metabolic effects, including insulin secretion, beta cell proliferation, slowing of gastric emptying and increased satiety; all are desirable features of type 2 diabetes therapy." (PMID 25412338, 2014). "Protein tyrosine phosphatase 1B (PTP1B) is a key negative regulator of insulin and leptin signaling, which suggests that it is an attractive therapeutic target in type II diabetes and obesity." (PMID 24865376, 2014). "Levels of blood glucose and insulin increased after the induction of type 2 diabetes, and so did HOMA-IR index (P < 0.05)." (PMID 24511320, 2014). "In newly diagnosed Chinese patients with type 2 diabetes, the decreased insulin secretion, in particular the first phase of insulin secretion, is the main characteristic." (PMID 24772445, 2014). "PTP1B is a negative regulator of the insulin signaling pathway and is a potential therapeutic target, in particular for treatment of type 2 diabetes." (PMID 25364621, 2014). "Regardless of intensity, aerobic exercise was able to improve insulin sensitivity and phosphorylation by protein kinase B/Ak, and proved to be a good form of treatment and prevention of type 2 diabetes." (PMID 24728251, 2014). "The dopamine D1-like receptor agonist, fenoldopam, has been shown to improve peripheral insulin sensitivity in STZ-induced type 2 diabetic rats." (PMID 24888351, 2014). "Oral medications play an important role in the management of type 2 diabetes; insulin is often used after other treatments have failed." (PMID 25202328, 2014). "Our aim was to compare the effects of an intermediate acting human insulin (NPH) and a long-acting insulin analog, insulin glargine, in insulin naïve type 2 diabetes patients, stratified by the type of hyperglycemia (fasting or postprandial type)." (PMID 23880900, 2014). "On the one hand, in cross-sectional studies in RA patients showed that GC exposure was related to impaired fasting insulin sensitivity and tended to predict development of type 2 diabetes." (PMID 25181348, 2014). "When starting bedtime insulin in type 2 diabetes patients, those with fasting type hyperglycemia are prone to greater weight gain." (PMID 23880900, 2014). "For example, antidiabetic drugs of the thiazolidinedione family are believed to target the transcription factor PPARG to improve insulin sensitivity in type 2 diabetes (T2D) and induce glucose transporter 4 mRNA expression in fat and muscle." (PMID 25197274, 2014).
type 2 diabetes (continued). "At present, the major therapeutic drugs to treat type 2 diabetes are insulin secretagogues (sulfonylureas, meglitinides), insulin sensitizers (metformin, thiazolidinediones) and α-glucosidase inhibitors in both domestic and foreign markets." (PMID 24633252, 2014). "The opposite effects of insulin and glucagon in fuel homeostasis, the paracrine/endocrine inhibitory effects of insulin on glucagon secretion and the hyperglucagonemia in the pathogenesis of type 2 diabetes (T2D) have long been recognized." (PMID 25177371, 2014). "Subsequently it appears that both kinds of tea have favorable effect on patients with type 2 diabetes, but green tea has a better effect on insulin resistance indices than the sour tea." (PMID 25242840, 2014). "Eventually, the beta cells cannot produce enough insulin and hyperglycemia (type 2 diabetes) results." (PMID 24824753, 2014). "It has well been known that type 2 diabetes is a multiorgan disease characterized by impaired insulin sensitivity and altered lipid metabolism and storage." (PMID 24511320, 2014). "A persistent increase in the gene expression of hepatic PCK, catalyzing the first, committed step of gluconeogenesis, leads to reduced ability of insulin to suppress hepatic glucose output, a change which is characteristic of type 2 diabetes." (PMID 24740266, 2014). "Decreased beta cell mass and inability to secrete appropriate amounts of insulin are classical features of gestational as well as type 1 and type 2 diabetes." (PMID 24967820, 2014). "Our results suggest glucocorticoid blockade is equally efficacious in individuals with Type 2 diabetes and increased liver fat, despite the multiple sites of greater insulin resistance found in these individuals." (PMID 25104497, 2014). "Declining beta cell function is a major contributing factor to the progressive nature of type 2 diabetes, with many patients eventually requiring insulin therapy to achieve and maintain glycaemic control." (PMID 24585202, 2014). "In conclusion, the results of this retrospective meta-analysis suggest that geriatric patients with type 2 diabetes can be treated with insulin lispro to achieve the same level of metabolic control as in non-geriatric patients." (PMID 23959960, 2014). "Here we studied the effects of moderate glycemic control (blood sugar: 90 - 150 mg/dL), after CABG, on blood gases in 18 patients with type II diabetes and 31 non diabetic controls, using continuous insulin infusion." (PMID 25478539, 2014). "Diabetic patients affected by type 2 diabetes on the other hand are usually treated with insulin sensitizers to enhance body's response to the endogenously secreted insulin." (PMID 24860609, 2014). "Type 2 diabetes (T2D) is a chronic metabolic disorder, which results from impaired insulin secretion and action in target tissues." (PMID 25401107, 2014). "Metformin, an insulin sensitiser, is the first-line oral antihyperglycemic drug used in the management of type 2 diabetes mellitus." (PMID 25139174, 2014). "Whole grain consumption was inversely associated with type 2 diabetes, a higher waist-to-hip ratio, LDL-cholesterol and fasting insulin." (PMID 25365577, 2014). "The automated texting of literature for the relationship of the interplay module genes and T2D was by the query terms that contained these genes and type 2 diabetes /insulin for the co-occurrence either in an abstract or in the title of previous publications." (PMID 24565181, 2014). "In the treatment of lifestyle diseases, including metabolic syndrome and type 2 diabetes, it is important to lower body mass and fat tissue, and consequently, to increase insulin-sensitivity." (PMID 25015881, 2014). "An identification of insulin resistant adolescent is highly important as the occurrence of type 2 diabetes coincides with the peak of pubertal IR." (PMID 25419241, 2014).
type 2 diabetes (continued). "Use of ER chaperones proved a beneficial therapy for treatment of type 2 diabetes as it restored systemic insulin sensitivity, normalized hyperglycemia, resolved fatty liver disease, and enhanced insulin action in various tissues." (PMID 24904422, 2014). "Type 2 diabetes is a polygenic disorder characterized by defects in insulin secretion and peripheral insulin resistance." (PMID 25165692, 2014). "For the treatment of patients suffering from type 2 diabetes, aside from life-style alterations, insulin and insulin analogs were first applied." (PMID 25083916, 2014). "In type 2 diabetes, several mechanisms have been proposed by which insulin resistance and exercise capacity are related." (PMID 24612649, 2014). "In both type 1 (T1D) and type 2 diabetes (T2D), the deterioration of glycemic control over time is primarily caused by an inadequate mass and progressive dysfunction of β-cell, leading to the impaired insulin secretion." (PMID 25147566, 2014). "Based on China Type 2 Diabetes Guideline (2010)Tips-Emphasize the importance of taking oral medication or insulin in accordance with general practitioner’s prescription." (PMID 25383608, 2014). "Pioglitazone, peroxisome proliferator-activated receptor (PPAR)γ agonist, is an insulin-sensitizing agent available for treatment of type 2 diabetes." (PMID 24772450, 2014). "On the other hand, repaglinide, a meal-time insulin secretagogue approved for treatment of type 2 diabetes, reduces postprandial blood glucose (PBG) peaks, lowers 24-h blood glucose (BG) profiles, and reduces HbA1c levels." (PMID 24843385, 2014). "IGF-binding protein (IGFBP)-1 levels are suppressed in relation to the increase in insulin levels in obesity and low levels predict the development of type 2 diabetes several years later." (PMID 26237614, 2014). "This is an indication that the islets are losing the ability to secrete insulin efficiently, a condition also seen in islets recovered from type 2 diabetic patients." (PMID 25198535, 2014). "Nineteen patients (32.8%) presented with diabetes mellitus type II with either oral medication or insulin therapy." (PMID 25375257, 2014). "Several oral diabetic agents, with actions such as enhancement of insulin sensitivity in insulin target organ and insulin secretion from pancreas, have been approved for type 2 diabetes management so far." (PMID 24772450, 2014). "By separating individuals using dispensed insulin or oral anti-diabetics and those using both, we attempted to distinguish between individuals with type 1 and type 2 diabetes." (PMID 25475416, 2014). "Our retrospective study suggests an interaction of thyroid diseases with metabolic control in type 2 diabetes resulting in an earlier need of insulin treatment." (PMID 24580798, 2014). "Patients with type 2 diabetes in whom the initial manifestation of insulinoma included a decreased demand for insulin or even a normalization of glycemia have also been described in literature." (PMID 25202394, 2014). "Dedifferentiation of these cells has been suggested to occur in type 2 diabetes, impairing insulin production." (PMID 25070369, 2014). "It has demonstrated that CML patients with type 2 diabetes have markedly elevated levels of adiponectin, implicating a mechanism for improved insulin sensitivity in the peripheral tissues." (PMID 24835010, 2014). "In this study, the cluster analysis revealed that the amino acid profiles were different depending on the insulin level in type 2 diabetic patients, and higher plasma concentrations of Glu, Pro, BCAAs and Tyr were observed in the higher insulin group." (PMID 25177913, 2014). "We focused on type 2 diabetes patients who had been admitted for insulin-treatment and diagnosed thyroid diseases (n = 328)." (PMID 24580798, 2014). "A number of other short-term studies have also reported that whey-protein has insulinotropic properties that can improve insulin sensitivity and glycaemic control in people with type 2 diabetes." (PMID 25376884, 2014).
type 2 diabetes (continued). "Elevated levels of those metabolites in fasting blood also characterize an insulin-resistant state and type 2 diabetes." (PMID 25106484, 2014). "The results of this study suggested that liraglutide had good efficacy and was well-tolerated in type 2 diabetic patients with ESRD switching from insulin therapy to liraglutide and requiring hemodialysis." (PMID 25526642, 2014). "In patients with type II diabetes mellitus osteoblasts increased their cell division and proliferation in presence of insulin (1.2- to 1.7-fold) but the ALP activity and the production of mineralized matrix was reduced to 55% in comparison to control." (PMID 24696682, 2014). "A class of PPARγ ligands called thiazolidinediones (TZDs), such as rosiglitazone and pioglitazone, has been introduced in clinical practice for improving glycemic control via insulin sensitization in patients with type 2 diabetes." (PMID 24693278, 2014). "At least 50% of people with type 2 diabetes have poor glucose control despite drug treatment and are often faced with the prospect of the addition of another oral drug or insulin." (PMID 25343850, 2014). "Despite being widely prescribed in type 2 diabetes, insulin administration correlates with higher mortality rates, and hyperinsulinemia is a factor in multiple diseases, including hypertension, fatty-liver disease, PCOS, Alzheimer's disease, and more." (PMID 24949486, 2014). "GPs saw the PN role as complementary to their own and that with adequate training they should be able to manage uncomplicated type 2 diabetes together, including initiating and managing insulin if there were clearly defined guidelines and protocols." (PMID 24479762, 2014). "The objective of this retrospective study was to compare the effect of human NPH insulin and a long-acting insulin analog glargine in insulin naïve type 2 diabetes patients, stratified by the type of hyperglycemia." (PMID 23880900, 2014). "Patients with concomitant appearance of the two endocrine disorders (group 2) required more often immediate insulin therapy despite their diagnosis of type 2 diabetes." (PMID 24580798, 2014). "Circulating levels of APN are reduced in obesity and type 2 diabetes, whereas improvement in insulin sensitivity upon treatment with thiazolidinediones correlated with increased APN levels." (PMID 24836538, 2014). "Matsuda IR, Adipocyte IR and fasting plasma insulin levels had comparable ability to predict incident type 2 diabetes and CVD events." (PMID 25310839, 2014). "Type 2 diabetes is a metabolic disorder resulting from the interplay between insulin secretion and action." (PMID 25145545, 2014). "SNPs within NPC1 have been associated with obesity and type 2 diabetes, and mice heterozygous or null for NPC1 are insulin resistant." (PMID 24752197, 2014). "Patients with type 2 diabetes have lower glucose uptake ability by insulin and insulin-independent signaling pathways due to increased fat mass or impaired mitochondrial function." (PMID 25089253, 2014). "The Ex11− form binds insulin with two-fold higher affinity than the Ex11+, a form which is more abundantly expressed in target tissues from the type 2 diabetic patients." (PMID 25988147, 2014). "The impairment of insulin secretion derived from β cell dysfunction is a progressive process that occurs before diagnosis and throughout the course of type 2 diabetes." (PMID 24684803, 2014). "To investigate the metabolic effects of reducing cortisol action in individuals with Type 2 diabetes we have tested the effects of acutely reducing cortisol action on the key metabolic pathways regulated by insulin." (PMID 25104497, 2014). "Regular aerobic exercise decreases cardiovascular risk of people with type 2 diabetes mellitus (T2DM) principally by reducing body weight and abdominal visceral fat accumulation with subsequent improvements in insulin sensitivity, blood pressure, lipid profile, and glycemic control." (PMID 27437465, 2014).
type 2 diabetes (continued). "Human subjects with type 2 diabetes exhibit increased activity of NF-κB in muscle that directly correlates with impaired insulin mediated glucose disposal." (PMID 24987732, 2014). "A total of 394 patients with type 2 diabetes treated with metformin and sulfonylurea (S+M group, n = 299) or metformin and insulin (I+M group, n = 95) were consecutively recruited." (PMID 25299054, 2014). "Previous work has shown that type 2 diabetics display an insulin resistance to amino acid infusion; however, in this study a mixed-meal does not appear to impair anabolic insulin signalling in the muscle of middle age men with MetS." (PMID 25302072, 2014). "App knockout mice exhibited increased insulin secretion in response to glucose, suggesting mechanistic similarities between the neurodegenerative disease and type 2 diabetes." (PMID 24752583, 2014). "The Lanmet study was a randomized, 36-week controlled insulin initiation study in type 2 diabetes patients." (PMID 23880900, 2014). "The insulin-resistant JCR:LA-cp rats are a good model for human type II diabetes in that they are insulin resistant, obese, and prone to atherosclerosis." (PMID 24408111, 2014). "The glucotoxicity that takes place in pancreatic islet β-cells results in reduction of insulin secretion and overt type 2 diabetes." (PMID 24704640, 2014). "As does endogenous GLP-1, liraglutide potentiates insulin secretion, improves HbA1c, and reduces post-prandial glucose levels in patients with Type 2 diabetes." (PMID 24835252, 2014). "This suggests defects in insulin secretion are important in the disease; an idea supported by work in humans and in other models of type 2 diabetes, such as the Goto-Kakizaki (GK) rat." (PMID 24705605, 2014). "When administered with a meal, glutamine increases GLP-1 and insulin excursions and reduces postprandial glycaemia in type 2 diabetes patients." (PMID 25412338, 2014). "Appreciating the many important differences in type 1 and type 2 diabetes, the common characteristics of hyperglycemia and decreased cellular insulin signaling are potential mediators of the cellular abnormalities that are observed in both." (PMID 24658034, 2014). "It is suggested that a similar pathogenesis operates in AD as in Type 2 diabetes (T2D), but restricted to the brain, thus describing AD primarily as a result of cerebral insulin resistance." (PMID 25231068, 2014). "Pramlinitide, an injectable amylin analog, is FDA approved for the treatment of type 1 diabetes and insulin treated type 2 diabetes and administered subcutaneously at mealtimes." (PMID 26237392, 2014). "The debate continues to the role of insulin (analogs) when high (supraphysiological) doses of insulin (analogs) are used in the treatment of type 2 diabetes in an attempt to achieve normoglycemia." (PMID 24904529, 2014). "In light of this study, future research should address the following question: Does the high normal level of S-P signal insulin resistance in smokers and in patients with type 2 diabetes?" (PMID 24636522, 2014). "In type 2 diabetic mice LEP improves hepatic insulin sensitivity by reducing gluconeogenesis which should be associated with the negative correlations between LEPR mRNA vs. glucose and insulin." (PMID 24465964, 2014). "Impairment in insulin sensitivity is present already at relatively low plasma glucose levels within the normoglycemic range, years before the development of overt type 2 diabetes." (PMID 25174260, 2014). "Hyperlactacidemia is found in patients with obesity and type 2 diabetes, which supports the strong relationship between acidic condition and insulin sensitivity." (PMID 25302301, 2014). "Agonists of PPARγ rosiglitazone and pioglitazone have been widely used for many years for treating type 2 diabetes, owing to their effectiveness in promoting insulin sensitivity." (PMID 24693278, 2014).